CASP5 (caspase 5)
Diseases named in the same sentence as CASP5 in open-access papers (continued):
Sharing a sentence is not in itself a finding about the gene and the disease.
infection (14 papers, 2015 to 2026). The state of being infected such as from the introduction of a foreign agent such as serum, vaccine, antigenic substance or organism. "Paralleling the impact of caspase-4 and caspase-5 on IL-1β release, during infection with M. kansasii, their absence was associated with a twofold reduction in cell death to baseline." (PMID 40272180, 2025). "Cell death and IL-18 release were significantly reduced in unprimed and IFN-γ-primed hMDMs treated with CASP4 or both CASP4 and CASP5 siRNA prior to infection with T4SS+ Lp, compared to control siRNA-treated cells." (PMID 37737612, 2023). "The data also indicated that caspase-4 and caspase-5 mRNA levels were greatly elevated after 4h post-infection." (PMID 37180156, 2023). "Consistent with previous reports studying STM-infection in human epithelial models, we did measure a significant increase in Caspase-4 and Caspase-5 transcript levels." (PMID 36191054, 2022). "WT THP-1s treated with either CASP4 or CASP5 siRNAs exhibited significantly decreased IL-1β secretion following WT Stm infection relative to WT THP-1s treated with control siRNA, in agreement with our previous observations in primary human macrophages." (PMID 35073381, 2022). "At 4 h of infection with M. kansasii and 24 h of infection with M. tuberculosis, the absence of caspase-4 and caspase-5 was associated with a complete absence of IL-1β release." (PMID 40272180, 2025). "Notably, the studies point to a specific importance for caspase-4 in mucosal immunity since caspase-4 expression level and ability to be activated in response to infection highly differs compared with caspase-5." (PMID 26426007, 2015). "Since caspase-1 inhibitor AC-YVAD-CMK also shows inhibitory activity against caspase-4 and caspase-5, which also belong to inflammatory caspases, we asked the question whether caspase-1 plays a prominent role in pyroptosis during the infection of CVB3 and EV71." (PMID 29440739, 2018). "Despite both caspase-4 and -5 possessing the ability to bind LPS, caspase-5 expression is inducible by LPS similar to caspase-11; however caspase-4 is constitutively expressed in human epithelial cells and is reported to be only modestly induced upon infection." (PMID 26426007, 2015). "Together, these data indicate that caspase-1, caspase-4, and caspase-5 are processed into their mature forms upon IFN-γ priming and infection with T4SS+ Lp." (PMID 37737612, 2023). "CASP5 expression was also up-regulated in infected samples, while CASP7 and CASP10 expression served as controls that were unaffected by infection status." (PMID 35588457, 2022). "The primary function of caspase-5 is to induce inflammation upon infection with intracellular Gram-negative bacteria." (PMID 38785927, 2024). "Caspase-5 is upregulated at the mRNA level and activated at the protein level by lipopolysaccharide (LPS), a critical molecule in infections with Gram-negative bacteria." (PMID 38785927, 2024). "NAIP-/- and NLRC4-/- THP-1s treated with CASP5 siRNA showed a slight but significant decrease in IL-1β secretion following CASP5 siRNA treatment, but not CASP4 siRNA treatment, compared to control siRNA-treated cells following WT Stm infection." (PMID 35073381, 2022). "Evidence for CASP5-driven pyroptosis in response to infection has not yet been established." (PMID 41705852, 2026). "Unprimed, mock-infected primary hMDMs had basal caspase-5 expression, and IFN-γ priming led to processed caspase-5 p35 subunit in primary hMDMs and THP-1 cells, suggesting that caspase-5 may be constitutively expressed and undergoes some autoprocessing regardless of infection status." (PMID 37737612, 2023).
bacterial infections (2 papers, 2022 to 2023). "The non-canonical inflammasome, which includes caspase-11 in mice and caspase-4 and caspase-5 in humans, is upregulated during inflammatory processes and activated in response to bacterial infections to carry out pyroptosis." (PMID 38106412, 2023).
CASP5 also shares sentences with these, for which no sentence is quoted: colorectal cancer (4 papers); adenocarcinoma (2); atherosclerosis (2); cervical cancer (2); clear cell renal cell carcinoma (2); osteosarcoma (2); asthma (1); autoimmune disease (1); chronic liver failure (1); conjunctivitis (1); depression (1); diabetes (1); E. coli infection (1); endometrial cancer (1); fibromyalgia (1); hematologic disorder (1); Henoch-Schönlein purpura (1); infectious disease (1); inflammatory skin disease (1); juvenile idiopathic arthritis (1); Kawasaki disease (1); kidney diseases (1); leukemia (1); leukocytosis (1); lung adenocarcinoma (1); lupus erythematosus (1); lymphoma (1); lymphopenia (1); Lynch syndrome (1); metastatic melanoma (1).
A further 11 diseases each share a sentence with CASP5 in 1 paper.